OTUD6B (OTU deubiquitinase 6B)
Diseases named in the same sentence as OTUD6B in open-access papers (continued):
Sharing a sentence is not in itself a finding about the gene and the disease.
cancer (continued). "Thus, the effect of OTUD6B deficiency on cell survival was restricted to the TNBC cells, consistent with the idea that it is a cancer-specific target." (PMID 39789388, 2025). "As kinesins are relatively difficult to target pharmaceutically, and complete inhibition of KIFC1 may have non-cancer cell specific effects, targeting OTUD6B has the potential to be developed as a more tolerable therapeutic route." (PMID 39789388, 2025). "Investigating the roles of OTUD6B-1 and OTUD6B-2 in cancer separately might more accurately assess the link between OTUD6B and cancer progression, thus opening up a new field of cancer-specific therapy." (PMID 41050073, 2025). "As OTUD6B may represent a legitimate target to promote cancer-specific cell death by inducing multipolar spindles, we tested the requirement of OTUD6B for viability of centrosome-amplified TNBC cells." (PMID 39789388, 2025). "As our data suggest that OTUD6B may also be required to cluster supernumerary centrosomes in cancer cells, we next examined how OTUD6B expression relates to KIFC1 expression, centrosome amplification and patient outcomes." (PMID 39789388, 2025). "Considering that the two shear isoforms of OTUD6B have opposing roles in cancer progression, this may explain the opposite roles of OTUD6B in different cancer types." (PMID 41050073, 2025). "Furthermore, we analyzed the association between the IHC score of OTUD6B in patient cancer tissue and TNM stage and observed that the higher the IHC score of OTUD6B in cancer tissue was, the greater the value of TNM stage in that patient." (PMID 38880876, 2024). "Here we conducted a pan-cancer analysis of OTUD6B to identify its impact on other cancer types." (PMID 36052059, 2022). "We firstly evaluated the OTUD6B expression in normal and cancer tissues in pan-cancer." (PMID 36052059, 2022). "The expression pattern of OTUD6B in pan-cancer was subsequently evaluated." (PMID 36052059, 2022). "Therefore, further studies to evaluate the potential value of OTUD6B in diagnosis and prognosis in cancers need to be carried out." (PMID 36052059, 2022). "As human homologues of the murine pre-diagnostic antigens exist and the proteins appear to be expressed in human pre-invasive breast lesions, we explored the potential utility of three of the antigens, Pdhx, Otud6B, and Stk39 in discriminating women who would eventually develop cancer from controls." (PMID 24886063, 2014). "However, the functional role and specific mechanism of OTUD6B in other cancers remain a mystery." (PMID 36052059, 2022). "OTUD6B catalytic activity is required to maintain KIFC1 levels and limit multipolar spindle formation, promoting the survival of cancer cells with supernumerary centrosomes." (PMID 39789388, 2025). "In this review, we comprehensively summarize the roles of seven DUBs with OTU structural domains in cancer progression and antiviral immune responses, including OTUD1, OTUD2, OTUD3, OTUD4, OTUD5, OTUD6A, and OTUD6B." (PMID 41050073, 2025). "Together, these findings highlight OTUD6B as a DUB that maintains KIFC1 levels to ensure supernumerary centrosomes remain clustered, allowing cancer cells to avoid mitotic catastrophe and complete cell division." (PMID 39789388, 2025). "Taken together, these data suggest a potential oncogenic role for OTUD6B and support the idea that OTUD6B maintains KIFC1 protein levels in cancer cells." (PMID 39789388, 2025). "We discovered that circPTPN12 serves as a scaffold, facilitating the interaction between PDLIM2 and OTUD6B, promoting PDLIM2 deubiquitination, maintaining its expression, and exerting its anti-cancer function." (PMID 38992675, 2024). "OTUD6B expression was upregulated in most cancers, such as COAD, CHOL, and LUAD, and predicted poor prognosis in most cancers in TCGA." (PMID 36052059, 2022). "OTUD6B expression was positively related with KICH, LUAD, and STAD, while it was negatively related with the other five cancers." (PMID 36052059, 2022).
cancer (continued). "Besides OTUB1, other DUBs, such as USPs family (USP1, USP7, USP8, USP15, USP22), OTUs family (OTUD7B, OTUD6B, A20, and OTUB2) and other DUBs have been identified to regulate the progression of various cancers and applied for clinical cancer therapy." (PMID 35715413, 2022). "The results revealed a positive correlation between OTUD6B expression and these genes in most types of cancer, while in SARC, TGCT, and STES, a negative correlation was observed." (PMID 36052059, 2022). "Utilizing ATRA to upregulate OTUD6B and subsequently stabilize the expression of its downstream DDX5, we hypothesized that targeting OTUD6B protein expression is a viable technique for combating cancer." (PMID 40651961, 2025). "Thus, in cancer cells lacking OTUD6B transcripts, ATRA would show little effects on promoting OTUD6B protein level and suppressing their TIC properties." (PMID 37038094, 2023). "Interestingly, the results also showed that OTUD6B expression was positively correlated with memory CD4+ T cells, Th2 CD4+ T cells, and CD8+ T cells and negatively correlated with Th1 CD4+ T cells in TCGA pan-cancer." (PMID 36052059, 2022). "OTUD6B may play a part in TIME, which could be applied as a new target for cancer therapy." (PMID 36052059, 2022). "Furthermore, we found that, like KIFC1, OTUD6B is a cancer-specific dependency, as its depletion reduced cell viability and colony formation in two TNBC cancer cell lines with centrosome amplification, but not in cells derived from normal breast." (PMID 39789388, 2025).
infection (2 papers, 2023). The state of being infected such as from the introduction of a foreign agent such as serum, vaccine, antigenic substance or organism. "Our data showed that OTUD6B overexpression suppressed infection by all these viruses, indicating the broad-spectrum antiviral effects of OTUD6B." (PMID 37650650, 2023). "The western blotting analysis of the probe-reacted deubiquitinases was used as a validation, where the level of USP14, USP15, OTUD6B and USP47 was diminished during infection with Y. enterocolitica at 18 hpi." (PMID 37026055, 2023). "Among these, one group containing OTUB1, OTUB2, OTUD4, OTUD5, OTUD6B, and OTUD7B showed obvious upregulation 6 h post-infection, followed by downregulation 12 h post-infection." (PMID 37650650, 2023). "Based on the mass spectrometric analysis, the THP-1 macrophages infected with Y. enterocolitica for 2 hours post-infection (hpi) had an increased level of USP4 and USP7 but decreased level of OTUD6B." (PMID 37026055, 2023).
genetic diseases (1 paper, 2018). "Two heterozygous splicing mutations were found in OTUD6B, a gene to which no genetic diseases had been associated when we completed exome data analysis (March 2017)." (PMID 30364145, 2018).
OTUD6B also shares sentences with these, for which no sentence is quoted: breast tumor (2 papers); Seizure (2); acute myeloid leukemia (1); cholangiocarcinoma (1); congenital heart disease (1); glioblastoma (1); glioma (1); head and neck squamous cell carcinoma (1); hydronephrosis (1); intellectual developmental disorder with dysmorphic facies, seizures, and distal limb anomalies (1); intrahepatic cholangiocarcinoma (1); kidney disease (1); laryngeal squamous cell carcinoma (1); melanoma (1); mesothelioma (1); microcephaly (1); nasopharyngeal carcinoma (1); osteosarcoma (1); ovarian carcinoma (1); pulmonary arterial hypertension (1); rectum adenocarcinoma (1); squamous cell carcinoma (1); thymoma (1); thyroid cancer (1); tongue cancer (1).